NOD2 (nucleotide binding oligomerization domain containing 2)
Diseases named in the same sentence as NOD2 in open-access papers (continued):
Sharing a sentence is not in itself a finding about the gene and the disease.
colorectal cancer (continued). "When NOD2 expression was blocked, the induction of autophagy by DEH was attenuated, suggesting that DEH-induced cell death in colorectal cancer cells at high concentrations may occur through the activation of NOD2 expression." (PMID 40468178, 2025). "Further research is also needed to investigate if NOD2 expression in phagocytes may favor colorectal cancer through limiting lysozyme-dependent anti-cancer properties such as direct activation of immune effectors and immunosuppressive antioxidant properties." (PMID 37876927, 2023). "Also, some individual pyroptosis genes have been studied, such as NOD2 in colorectal cancer, gasdermin B (GSDMB) in digestive system, and Gasdermin D (GSDMD) in gastric cancer." (PMID 36249755, 2022). "The types of cancers studied in relation to NOD2 polymorphisms included gastric cancer and MALT lymphoma, colorectal cancer (CRC), melanoma, endometrial cancer, pancreatic cancer, breast cancer, non-Hodgkin lymphoma, laryngeal cancer, lymphocytic leukaemia and ovarian cancer." (PMID 24586700, 2014). "Additionally, it promotes autophagy in colorectal cancer by modulating NOD2." (PMID 40468178, 2025). "Most likely due to the overall rare occurrence of colorectal cancer, we could only find this association for NOD2 rs2066844, but not for NOD2 rs2066845 or NOD2 rs2066847." (PMID 34198814, 2021). "Modulating the NOD2/TNF-α signaling axis to balance the induction of mo-DCs and repression of mo-Macs appears to be a promising new target for immunotherapy of colorectal cancer and to treat stricturing complications of CD patients." (PMID 37415975, 2023). "NOD1 and NOD2 expression were enhanced in colorectal cancer, and NLRC5, NLRP6 and NLRP12 had no significant changes compared to the controls." (PMID 34571825, 2021). "The lysozyme in phagocytes may participate by various mechanisms in the reduction of inflammation and colorectal cancer in the absence of Nod2-mediated signaling." (PMID 37876927, 2023). "Ten SNPs in the following six genes: NOD2 (2140 C/T, 2722 G/C), DLG5 (113 G/A), OCTN1 (1672 C/T), OCTN2 (-207 G/C), IL4 (-590 C/T) and TNFα (-308 G/A, -857 C/T, -863 C/A, -1031 T/C) were screened in a consecutive series of colorectal cancer patients using a two-staged approach." (PMID 18433468, 2008).
Insulin resistance (27 papers, 2012 to 2025). Increased resistance towards insulin, that is, diminished effectiveness of insulin in reducing blood glucose levels. "Beyond detecting MDP and triggering the pro‐inflammatory response, NOD2 protein has recently been associated with the development of Crohn′s disease, as well as oxidative stress and insulin resistance." (PMID 41340462, 2025). "Similar to the TLR system, the nucleotide-binding oligomerization domain contains the proteins NOD1 and NOD2, which are cytosolic receptors that respond to bacterial peptidoglycans and have been associated with the development of insulin resistance." (PMID 37373556, 2023). "In one study, the carriage of non-synonymous polymorphisms of NOD1 (rs2075820 [p.E266K]) and NOD2 (rs2066842 [p.S268P]) was examined for links with metabolic syndrome and insulin resistance in 998 Canadians aged 20–29." (PMID 33503814, 2021). "A handful of studies have evaluated specific NOD1 and NOD2 polymorphisms to determine if they are associated with metabolic syndrome and insulin resistance." (PMID 33503814, 2021). "Both NOD1 and NOD2 have been linked with innate immune system activation in metabolic disease, including insulin resistance, diabetes, and liver steatosis." (PMID 33503814, 2021). "NOD1 and NOD2 are cytosolic receptors that respond to bacterial peptidoglycans and have been associated with the development of insulin resistance." (PMID 33178196, 2020). "After these proof-of-principle experiments, we found that a 16-week HFD commonly used to cause insulin resistance increased bacterial DNA in the liver of only NOD2−/− mice." (PMID 25666722, 2015). "As well supported by the inspection of microbiota in NOD2-deficient mice, an intact NOD2 peptidoglycan-sensing system is actively involved in metabolic inflammation and insulin resistance and counteracts excessive dysbiosis-linked inflammation and insulin resistance." (PMID 38999827, 2024). "Administration of MDP to myotube cells in vitro significantly impairs insulin-stimulated glucose uptake and activates proinflammatory cytokine release, suggesting a direct causal relationship between NOD2 activation and insulin resistance in skeletal muscle cells in vitro." (PMID 35531300, 2022). "Our findings demonstrate that NOD2 deficiency contributes to the disruption of the intestinal barrier, serum LPS leakage, which is a possible mechanism that results in metabolic inflammation and insulin resistance worsening in these mice." (PMID 32774333, 2020). "Genetic variants of NOD2 may also influence the risk of chronic inflammation, insulin resistance, and T2D." (PMID 31212707, 2019). "The presence of MDP, a significant element of bacterial cell walls in the gut, activates the nucleotide-binding oligomerization domain 2 (NOD2), which triggers a proinflammatory signaling cascade that contributes to insulin resistance." (PMID 40936935, 2025). "Based on our collected data, it is difficult to draw definitive conclusions regarding the involvement of NOD2 in the development of podocyte insulin resistance, which represents a limitation of our research and requires further studies." (PMID 41340462, 2025). "It therefore appears that the role of NOD2 in the development of insulin resistance and other metabolic disorders is highly tissue‐specific." (PMID 41340462, 2025). "Research on the nucleotide-binding oligomerization domain containing 2 (NOD2) suggests its central role in linking inflammation and podocyte insulin resistance in diabetic nephropathy." (PMID 40698245, 2025). "The activation of NOD2 via bacterial cell-wall-derived muramyl dipeptide (MDP) improved insulin resistance." (PMID 37373556, 2023). "Direct NOD1 activation led to insulin resistance while, conversely, NOD2 signaling is protective against Type 2 diabetes." (PMID 37373556, 2023).
Insulin resistance (continued). "In parallel with the NOD1-mediated adipocyte and hepatocyte inflammations in insulin resistance, NOD2 activation by the corresponding PGN ligands in skeletal muscle cells also provoked insulin resistance via cell-autonomous innate immune responses." (PMID 35531300, 2022). "A role for NOD1 and NOD2 in HFD-induced insulin resistance was first demonstrated in Nod1/2−/− mice on a C57BL/6 background." (PMID 33503814, 2021). "For example, a study of 25 Indian diabetic patients showed that diabetic monocytes had significant upregulation of both Nod1 (20 fold) and Nod2 (25 fold) transcripts that positively correlated with insulin resistance." (PMID 33503814, 2021). "Similar to the results on HFD-induced insulin resistance, both whole body and hepatocyte-specific Nod2 knockout mice exhibited higher levels of liver steatosis and fibrosis when fed a NAFLD-inducing diet." (PMID 33503814, 2021). "Further, the ADSC-injected mice displayed lower levels of macrophage (F4/80+) infiltration, interleukin-6 (IL-6), and nucleotide-binding oligomerization domain 2 (NOD2) in liver tissue, resulting in improved insulin resistance." (PMID 33957965, 2021). "HFD-fed NOD2−/− mice also demonstrated more insulin resistance, as shown by the ITT test, and higher levels of serum insulin in comparison to WT mice on the HFD, confirming a state of hyperinsulinemia." (PMID 32774333, 2020). "Defective NOD2 sensing promotes diet-induced inflammation, microbial changes and insulin resistance." (PMID 33178196, 2020). "Overall, our data imply that NOD2 activation reinforces the intestinal barrier function and inhibits LPS translocation, which control insulin resistance and T2D onset induced by HFD." (PMID 32774333, 2020). "NOD2 activation via bacterial cell wall-derived muramyl dipeptide (MDP) improved insulin resistance." (PMID 33178196, 2020). "We demonstrate here that defective NOD2 sensing of PGN, either by NOD2 gene deletion or by mutations in PGN, promotes an increased bacterial invasion of metabolic tissues associated with inflammation and insulin resistance." (PMID 25666722, 2015). "Peptidoglycan-induced activation of NOD1 in adipocytes or hepatocytes and NOD2 in muscle cells trigger insulin resistance through the production of inflammatory mediators and the activation of MAP kinases signaling leading to desensitization of IRS1 function." (PMID 23316186, 2012). "However, other studies suggest that NOD2 activation contributes to insulin resistance and impaired glucose tolerance, particularly in muscle cells." (PMID 41340462, 2025). "However, the mechanism by which NOD2 influences NSPs and the development of insulin resistance requires further detailed investigation." (PMID 41340462, 2025). "The role of NOD2 in the development of insulin resistance appears to be counterintuitive." (PMID 41340462, 2025). "The poor functioning of NOD2 increases inflammation and insulin resistance." (PMID 37373556, 2023). "Furthermore, the deletion of NOD2 exacerbates diet-induced insulin resistance as NOD2 sensing of bacterial peptidoglycan provides protection from metabolic defects." (PMID 32722085, 2020). "In summary, NOD2 deletion contributes to insulin resistance during a HFD." (PMID 25666722, 2015). "Hence, we evaluated the transmissibility of the NOD2-related insulin resistance phenotype to WT germ-free mice, where all donor and recipient mice were fed a HFD." (PMID 25666722, 2015). "It was found that NOD2 could potentially mediate the development of insulin resistance." (PMID 41340462, 2025). "Metabolic inflammation and insulin resistance are driven by the sensing of translocated intestinal microbiota by NOD1, which is downregulated by the activation of NOD2." (PMID 36268029, 2022).
Insulin resistance (continued). "NOD2 expressed in non-hematopoietic cells, rather than in hematopoietic cells, protects against insulin resistance and metabolic inflammation, because hepatocyte-specific NOD2 deletion resulted in the development of severe steatosis and hepatic fibrosis." (PMID 36268029, 2022). "Unlike NOD1-knockout mice, animals deficient in NOD2 showed no protection to insulin resistance during HFD and even had increased adipose tissue and liver inflammation as well as exacerbated insulin resistance." (PMID 31632962, 2019). "Intriguingly, the activation of either NOD1 or NOD2 leads to different outcomes in mouse models of T2DM: NOD1/2 double-knockout mice and NOD1 knockout mice were protected from HFD-induced insulin resistance." (PMID 31632962, 2019). "We previously showed that obese high-fat diet (HFD)-fed mice lacking both nucleotide oligomerization domain (NOD1) and NOD2 have reduced insulin resistance and inflammation." (PMID 25666722, 2015). "Furthermore, a bone marrow transplantation experiment revealed that non-hematopoietic expression of RIPK2 is required for the NOD2-mediated protection against insulin resistance and metabolic syndrome." (PMID 36268029, 2022). "Interestingly, the absence of NOD2 in male mice fed a HFD exacerbates insulin resistance independently of an increase in body mass, promotes bacteria translocation, and inflammation in metabolic tissues." (PMID 32774333, 2020). "Nucleotide-binding oligomerization domain containing 2 (NOD2), a member of the NOD-like receptor family, has been found to be one of the critical components of a signal transduction pathway linking renal injury to inflammation and podocyte insulin resistance in diabetic nephropathy." (PMID 28900628, 2017). "Our current working model proposes that NOD1 deletion is protective, but to the best of our knowledge, no study has shown that defective PGN sensing by NOD2 may interact with a dietary stress to promote worse insulin resistance." (PMID 25666722, 2015). "We did not consider that NOD2 deletion could worsen insulin resistance and the dietary stress during this 70% HFD was not suitable to find (genetic) factors that potentially worsen insulin action or glucose regulation." (PMID 25666722, 2015). "NOD2 immunity may also to contribute to gut microbial homeostasis, but the relevance to metabolic disease and insulin resistance has not yet been fully explored." (PMID 25666722, 2015).
ulcerative colitis (26 papers, 2009 to 2026). An inflammatory bowel disease involving the mucosal surface of the large intestine and rectum. "Genomic DNA from 2256 Caucasians, including 1073 CD patients, 464 patients with ulcerative colitis (UC), and 719 healthy controls, was genotyped for the NOD2 SNP rs72796353 and the three main CD-associated NOD2 mutations rs2066844, rs2066845, and rs2066847." (PMID 26147989, 2015). "Furthermore, Leu1007ProfsTer2, one of the genetic variants of NOD2 identified in the hereby presented case, was shown to be associated with other clinical entities, such as psoriatic arthritis, rheumatoid arthritis, spondyloarthropathy and ulcerative colitis." (PMID 28750667, 2017). "The signaling of NOD2 involved in ulcerative colitis can be intricate, which is a result of their extensive distribution in various intestinal epithelium and immune cells and complicated downstream pathways, such as the NF-κB and MAPK signaling pathways." (PMID 37833958, 2023). "In 2002, a French group published an analysis of the NOD2 gene by direct DNA sequencing in 453 patients with CD, including 166 sporadic and 287 familial cases, 159 patients with ulcerative colitis (UC), and 103 healthy control subjects." (PMID 26147989, 2015). "Previous studies showed that the polymorphism in the promoter of the human CD14 gene was associated with CD and ulcerative colitis (UC), either alone or through interaction with polymorphisms in the CARD15/NOD2 gene." (PMID 22605977, 2012). "Variants in IL‐23R and NOD2 strongly influence IBD susceptibility, and recent work has highlighted how targeting the IL‐23/Th17 axis can translate these findings into effective biologic therapies in CD and ulcerative colitis." (PMID 41487707, 2026). "Under some circumstances, NOD2 can promote intestinal inflammation in ulcerative colitis." (PMID 37833958, 2023). "NOD2 was shown to be activated to stimulate the NF-κB and IF-17F pathways via CARD3 after Fusobacterium nucleatum (F. nucleatum) infection, which is associated with ulcerative colitis." (PMID 37833958, 2023). "In agreement with our hypothesis, successful results were observed in ulcerative colitis, in which NOD2 plays a minor role if any14,17." (PMID 36266398, 2022). "Thus, polymorphisms in genes, such as NOD2/CAR15, ATG16L1, IL23R, and IL10R have been involved in susceptibility to pIBD or to very-early-onset ulcerative colitis." (PMID 32397546, 2020). "A research reported that the NOD2 gene rs2066842 and rs2066843 polymorphisms showed a significant association with ulcerative colitis, but not with Crohn's in Indian patients (Pugazhendhi, Santhanam, Venkataraman, Creveaux, & Ramakrishna, 2013)." (PMID 30950247, 2019). "Of note, they were able to identify similar patterns in ulcerative colitis patients with NOD2 mutations, suggesting that the observed effect is not just one of disease phenotype." (PMID 29462388, 2018). "Other genes identified within the human IBD ‘granulocyte, myeloid’ module, including NOD2, FCGR3 and PROK2, which were most highly expressed in the biopsies from ulcerative colitis, were most highly abundant in the Maffl/flCd4Cre mice." (PMID 38609547, 2024). "In a recent study, supervised machine learning was used to classify IBD patients by subtype using whole exome sequecing (WES) data; NOD2 was found to be the top gene for discriminating CD and ulcerative colitis, regardless of gene panel used." (PMID 39372397, 2024).
Sepsis (25 papers, 2006 to 2025). Sepsis is defined as life-threatening organ dysfunction caused by a dysregulated host response to infection. "Three studies (including 229 cases and 943 controls) determined the association between NOD2 rs2066844 Arg702Trp and the risk of sepsis." (PMID 30683156, 2019). "R702W, G908R, and Leu1007fsinsC polymorphisms in the NOD2 gene were reported to be associated with sepsis susceptibility." (PMID 30950247, 2019). "There was an increased risk of sepsis associated with NOD2 rs2066844 Arg702Trp in the dominant model (OR = 2.25, 95% CI = 1.39–3.64, P = 0.001)." (PMID 30683156, 2019). "Sepsis occurred in about 60% of the patients with NOD2 variants and NOD2 wild-type alleles, respectively." (PMID 28765628, 2017). "In this study, we did not detect different levels of circulating IL-6 or neutrophil accumulation in the lungs during sepsis in Nod1-, Nod2-, Nod1/Nod2- and Rip2-deficient mice compared to WT septic mice." (PMID 25084278, 2014). "Neutrophil recruitment into the peritoneal cavity was assessed in Nod1- and Nod2-deficient mice following CLP-induced sepsis." (PMID 25084278, 2014). "NOD2 pathway polymorphisms were evaluated in relation to outcomes of episodes of sepsis, ICU admissions, hyperbilirubinemia and need for IT." (PMID 24465786, 2014). "NOD2 has, for instance, been reported to be associated with increased sepsis-related mortality in patients admitted to an Intensive Care Unit." (PMID 23977330, 2013). "Currently available data on human sepsis associations with NOD2 mutations indicate more prevalent bacteremia and higher sepsis-related mortality in ICU studies." (PMID 24086711, 2013). "The 3020insC mutation of the NOD2 gene is also associated with increased risk of sepsis in VLBW infants." (PMID 16611358, 2006). "Extracellular histone H3, whose stimulation could elevate the expression of NLRP3 and NOD2, caused pyroptosis in sepsis via NOD2 and VSIG4/NLRP3 pathways." (PMID 34868031, 2021). "Extracellular histone H3 induced by LPS could cause pyroptosis during sepsis via NOD2 and VSIG4/NLRP3 pathway." (PMID 34906145, 2021). "It has also been reported that the NOD2 variants are associated with reduced survival in sepsis." (PMID 25887140, 2015). "Interestingly, Nod2 polymorphisms have been associated with an increased susceptibility to sepsis in infant and adult patients." (PMID 25084278, 2014). "With regard to NOD2-targeted therapeutics for sepsis associated with bacterium, inhibition of NOD2 signals might be useful." (PMID 23675299, 2013). "Moreover, very recent study suggests that polymorphisms in the NOD2/Card15 gene might be related with susceptibility to sepsis in children." (PMID 23675299, 2013). "Some findings are consistent with our study, for instance, IL17A, IL1B, MBL, NOD2, PPARG and SOD2 genes were associated with sepsis." (PMID 40168842, 2025). "Severe COVID-19, ALI/ARDS and sepsis patients are all characterized by the activation and increased expression of TLR2, TLR4 and NOD2 (and sometimes NOD1, as well) and their associated synergisms (which are quite numerous)." (PMID 33672738, 2021). "Here, we evaluated the role of Nod1, Nod2 and MyD88-dependent signaling in the chemokine production and neutrophil recruitment to the infectious site during sepsis induced by cecal ligation and puncture (CLP) in C57Bl/6 mice." (PMID 25084278, 2014). "This study aimed to evaluate the role of the NLR family members Nod1 and Nod2 in the chemokines production and neutrophil recruitment to the infectious site in polymicrobial sepsis." (PMID 25084278, 2014). "Similar levels of MPO activity were observed in the lungs of WT, Nod1/Nod2- and Rip2-deficient mice 24 h after CLP-induced severe sepsis, further confirming that these pathogen sensors are not relevant to neutrophil sequestration in the lung." (PMID 25084278, 2014).